IL6 (interleukin 6)
Diseases named in the same sentence as IL6 in open-access papers (continued):
Sharing a sentence is not in itself a finding about the gene and the disease.
diabetic macular edema (23 papers, 2007 to 2025). "A meta-analysis revealed that elevated levels of VEGF, IL-6, and MCP-1 in aqueous humor are associated with DR risk, while VEGF, IL-6, IL-8, and MCP-1 correlate with diabetic macular edema (DME) risk." (PMID 41126323, 2025). "In the eye, significant elevation of IL-6 has been observed in ocular fluids (vitreous and aqueous) derived from retinal vein occlusion, diabetic macular edema, and refractory/chronic uveitis patients." (PMID 33101305, 2020). "Together with IL-6, serum concentrations of chitinase-3-like protein have been recently discovered as a novel biomarker for diabetic macular edema with serous RD." (PMID 33117608, 2020). "In cases of diabetic macular edema, retinal vein occlusion, and chronic uveitis, IL-6 has been found to be significantly elevated in ocular fluids." (PMID 31523783, 2019). "It has been recognized that the levels of IL-6 were raised in other ocular vascular diseases such as retinal vein occlusion and diabetic macular edema." (PMID 31523783, 2019). "Elevated levels of IL-6, IL-8, and MCP-1 in aqueous humor have been found to be associated with diabetic macular edema and to serve as predictors of this disease." (PMID 26641100, 2015). "According to previous studies, both VEGF and IL-6 in vitreous fluid was increased in patients with diabetic macular edema." (PMID 23675018, 2007). "Notably, intraocular IL-6 levels correlate with diabetic macular edema (DME) severity and directly contribute to barrier dysfunction." (PMID 41394857, 2025). "In addition to this, anti-IL-6 antibodies have been demonstrated to have beneficial effects in the treatment of diabetic macular edema." (PMID 37623898, 2023). "Vitreous and aqueous concentrations of VEGF and IL-6 may serve as biomarkers of disease progression, because they correlate with the severity of macular thickness alteration in diabetic macular edema." (PMID 37959396, 2023). "In addition, the levels of IL-6 are elevated in other ocular vascular diseases such as retinal vein occlusion and diabetic macular edema." (PMID 31523783, 2019). "In diabetic macular edema (DME), vascular endothelial growth factor (VEGF), hepatocyte growth factor (HGF), IL-6, and MCP-1 increase vascular permeability and promote angiogenesis in DR." (PMID 39634174, 2024). "Our results suggest that high levels of IL-1β, IL-6, and MCP-1 (proinflammatory and proangiogenic) and low levels of IL-10 (anti-inflammatory and anti-angiogenic) are involved in the pathogenesis of diabetic macular edema." (PMID 25923230, 2015). "Recent clinical studies showed that vitreous levels of cytokines, including interleukin-6 (IL-6), vascular endotheloial growth factor (VEGF) were increased in patients with diabetic macular edema(DME), and related to the severity of DME." (PMID 23675018, 2007). "A daily DHA-TG supplementation (lasting from 3 months to 3 years) improved total antioxidant capacity and reduced serum IL-6 in patients suffering from pseudoexfoliation glaucoma, non-proliferative DR or diabetic macular edema when compared to non-supplemented controls." (PMID 33921773, 2021). "Patients with diabetic macular edema without peripheral retinal ischemia detected by wide-angle fluorescein angiography showed a significant increase in the median level of interleukin 6 and a significant decrease in VEGF level after treatment with ranibizumab." (PMID 34907265, 2021).
Oral leukoplakia (23 papers, 2012 to 2025). A thickened white patch on the oral mucosa that cannot be rubbed off. "Another study also suggested enhanced production of salivary IL-6 as a diagnostic marker for leukoplakia and OSCC cells." (PMID 35484352, 2022). "In human saliva and serum, TNF-α, IL-8, and IL-6 exhibited an increasing trend among healthy individuals, oral leukoplakia patients, and OSCC patients (P < 0.05)." (PMID 41415031, 2025). "As the histological grade of differentiation increased in both OSCC and leukoplakia cases, there was a corresponding rise in salivary IL-6 levels." (PMID 38803729, 2024). "In conclusion, this study underscores the potential significance of IL-6 as a valuable biomarker in oral leukoplakia and OSCC." (PMID 38803729, 2024). "With a p-value of 0.000 (p 0.05), the rise in serum and salivary IL-6 levels in OSCC when compared to leukoplakia and the control group was very significant." (PMID 38803729, 2024). "The mean serum IL-6 levels in OSCC, leukoplakia, and the control group were 61.23 pg/mL, 19.07 pg/mL, and 3.1 pg/mL, respectively, whereas the mean salivary IL-6 levels were 93.6 pg/mL, 21.04 pg/mL, and 6.91 pg/mL, respectively." (PMID 38803729, 2024). "The OSCC group in this study had considerably greater mean salivary IL-6 concentrations than the Leukoplakia and control groups, with a p-value of 0.000 (p 0.05)." (PMID 38803729, 2024). "Similar to this, OSCC had significantly higher mean blood IL-6 concentrations than the Leukoplakia and control groups, with a p-value of 0.000 (p 0.05)." (PMID 38803729, 2024). "Many authors have been focusing on the role of interleukins and on their concentration in saliva samples of a patient with leukoplakia and IL-6, and 1L-8 are highest in people affected than in healthy people." (PMID 35888762, 2022). "Increased risk of oral precancerous lesions, such as leukoplakia, oral lichen planus, and OSMF, was induced by TNF-α (−308) and IL-6 gene polymorphism." (PMID 35982996, 2022). "Other research performed on patients diagnosed with oral leukoplakia showed that the levels of IL-6 and TNF in the saliva can be used as a proven significant clinical biomarker." (PMID 32899735, 2020). "Patients with clinically confirmed oral leukoplakia were registered to have significantly higher salivary concentration of Interleukin 6 (IL-6) when compared to healthy individuals." (PMID 31516665, 2019). "In oral leukoplakia patients, salivary samples were studied, and the levels of salivary interleukin-6 and TNF-α were found to be significant as clinical diagnostic markers." (PMID 28397778, 2017). "The findings indicate that IL-6 may play a pivotal part in the progression of oral leukoplakia and OSCC, positioning it as a promising prognostic marker." (PMID 38803729, 2024). "IL-6 and TNF-α were associated to distinguish OSCC versus oral leukoplakia." (PMID 36412636, 2022). "There is evidence that using IL-6 as a marker could be an indicator for periodontitis, leukoplakia and tobacco consumption habits." (PMID 36005252, 2022). "Moreover, within the leukoplakia group IL-6 level was found to be increased with increase in the severity of dysplasia." (PMID 32245251, 2020). "Furthermore, there is also a place for detection of cytokines in saliva, for example IL-6 in oral leukoplakia or IL-1, IL-6, IL-8, VEGF, and TNF-α in tongue squamous cell carcinoma." (PMID 32670885, 2020). "Moreover, salivary IL-6 and TNF-α alterations may be implicated in the pathogenesis of oral Leukoplakia." (PMID 35888762, 2022). "Salivary IL8 was considered an appropriate biomarker compared to the serum, and salivary IL6 was significantly elevated in OSCC and leukoplakia compared to controls." (PMID 36900301, 2023). "IL-6, alongside tumor necrosis factor alpha (TNF-α), was found to discriminate between OSCC and oral leukoplakia." (PMID 34830096, 2021). "The present study also confirmed the expression of IL-1α, IL-6, IL-8, and TNF-α in oral leukoplakia and oral lichen planus specimens." (PMID 32245251, 2020).
Oral leukoplakia (continued). "We decided to evaluate the panel of four proinflammatory, NF-kappaB dependent cytokines (IL-1α, IL-6, IL-8, and TNF-α) not only in saliva, but also in tissue specimens of OSCCs and OPMDs such as oral leukoplakia and oral lichen planus." (PMID 32245251, 2020). "Compared with healthy controls, the patients with oral lichen planus, oral leukoplakia, or OSMF all had elevated serum and salivary levels of TNF-α and IL-6, and the findings were supported by another research, revealing that TNF-α and IL-6 levels increased in OSMF patients." (PMID 35982996, 2022). "Furthermore, clinical studies have reported increased IL-6 serum levels and salivary IL-6 concentration in OSCC patients compared to patients with leukoplakia and healthy controls, suggesting that IL-6 could be a crucial biomarker in HNSCC diagnosis." (PMID 35484352, 2022). "Moreover, analysis of inflammatory cytokines in the serum of leukoplakia rats revealed significantly elevated levels of TNF-α and IL-6, further supporting the hypothesis that microbial dysbiosis triggers inflammatory pathways that contribute to tissue damage and disease progression." (PMID 41199950, 2025). "Concentrations of IL-6, IL-8, and TNF-α were also markedly higher in OSCC group as compared to subjects with oral leukoplakia without dysplasia (p = 0.0012, 0.0000, and 0.0492, respectively) and oral lichen planus without dysplasia (p = 0.0084, 0.0002, and 0.0212, respectively)." (PMID 32245251, 2020).
pancreatic adenocarcinoma (23 papers, 2003 to 2025). "To identify the association of IL-6 expression and the development of pancreatic adenocarcinoma, by using real time RT-PCR and immunoblot, we compared the IL-6 mRNA and protein levels in pancreatic adenocarcinoma with that in their adjacent nontumor tissues." (PMID 29693005, 2018). "The IL-8 concentration also seemed to be associated with or influenced by IL-6 and TNFα levels in patients with pancreatic adenocarcinoma." (PMID 24849506, 2014). "This study investigates the activation of the IL-6/GP130/JAK/STAT3 pathway in archived biopsy samples from patients with pancreatic adenocarcinoma, quantifying its expression in both tumor and stromal compartments." (PMID 41397158, 2025). "The pancreatic adenocarcinoma cohort was segregated into two groups based on the median expression of IL6." (PMID 40523922, 2025). "This study represents one of the first translational investigations of IL-6/GP130/JAK/STAT3 signaling in pancreatic adenocarcinoma." (PMID 41397158, 2025). "RLX has shown efficacy against pancreatic adenocarcinoma growth through ERβ and the IL-6/gp130/STAT3 signaling pathway interference in PDAC cell line." (PMID 35708464, 2022). "In pancreatic adenocarcinoma patients, IL-6 upregulates other cytokine expression and is involved in proliferation, resistance to apoptosis, and immune evasion." (PMID 29693005, 2018). "In this study, we demonstrated that suppression of IL-6 expression resulted in inhibition of in vitro and in vivo tumorigenicity of the pancreatic adenocarcinoma cells." (PMID 29693005, 2018). "The combined treatment dramatically inhibited tumor growth compared to either treatment alone, suggesting that shRNA targeting IL-6 sensitized the xenografted pancreatic adenocarcinoma cells to gemcitabine." (PMID 29693005, 2018). "In conclusion, our investigation provides evidence on the significance of shRNA targeting IL-6 in determining the tumorigenicity of pancreatic adenocarcinoma cells." (PMID 29693005, 2018). "Targeting the IL-6/glycoprotein 130 (GP130)/JAK/STAT3 axis may therefore represent a promising therapeutic approach for pancreatic adenocarcinoma." (PMID 41397158, 2025). "Considering the substantially important roles of STAT3 in the development and progression of a large number of cancer types, we speculated that blocking IL-6 expression in STAT3 signaling may be valuable in the treatment of pancreatic adenocarcinoma." (PMID 29693005, 2018). "In addition, knockdown of IL-6 expression sensitized pancreatic adenocarcinoma cells to gemcitabine." (PMID 29693005, 2018). "Our analysis demonstrated that IL-6, IL-8, IL-10, and TNFα are promising novel candidate markers for the detection of pancreatic adenocarcinoma, whereas IL-23 might be valuable for its ability to exclude a diagnosis of cancer." (PMID 24849506, 2014). "Therefore, the combination of gemcitabine and shRNA targeting IL-6 may become a potential clinical application for the treatment of pancreatic adenocarcinoma." (PMID 29693005, 2018). "Their activation by different factors, including, for example, IL-1, IL-6, TNF-α, TGF-β1, and activin 1, induces fibrosis and accounts for the desmoplastic property of pancreatic adenocarcinomas." (PMID 38891809, 2024). "This study aims to evaluate the activation of the IL-6/GP130/JAK/STAT3 signaling pathway in previously collected tissue samples—including pancreatic biopsies, surgical specimens, and liver biopsies—from patients diagnosed with pancreatic adenocarcinoma." (PMID 41397158, 2025). "Two CAR-T cells showed increased release of IFNγ, TNFα, IL-2 and very limited production of IL-6 after stimulated by four EpCAM positive pancreatic adenocarcinoma cells while not by hTERT–HPNE." (PMID 41417221, 2025).
pancreatic adenocarcinoma (continued). "We found that the IL-6 expression in the pancreatic adenocarcinoma was significantly higher than that in the adjacent nontumor tissues." (PMID 29693005, 2018). "We found considerably higher expression of IL-6 in pancreatic adenocarcinoma tissues than that in the adjacent nontumorous tissues." (PMID 29693005, 2018).
Peritoneal Fibrosis (23 papers, 2014 to 2025). Disorder characterized by a wide range of structural changes in PERITONEUM, resulting from fibrogenic or inflammatory processes. "Excessive fibrosis can impair organ function and compromise peritoneal dialysis efficiency, and elevated levels of IL-6 have been associated with poor prognosis in peritoneal fibrosis." (PMID 38689325, 2024). "IFN-γ deficiency resulted in significantly ameliorated S. epidermidis-induced peritoneal fibrosis while adoptive transfer of Th1 cells induced fibrotic progression in fibrosis-resistant IL-6 deficient mice." (PMID 32708044, 2020). "Taken together, these findings suggested that STAT3 contributed to TGFβ‐induced and IL‐6/S‐induced activation of fibroblasts and was involved in progressive peritoneal fibrosis." (PMID 38780509, 2024). "We treated both ADSC and BM-MSC with TGF-β1, a pleiotropic cytokine released in the peritoneal cavity and the main mediator of peritoneal fibrosis, then measured IL-6 in the medium." (PMID 33741073, 2021). "The dialysate IL-6 level is increased shortly before the onset of and during the peritoneal fibrosis and several months after the clinically cured peritonitis, suggesting its local production and reflecting an intraperitoneal fibrosis and inflammatory state." (PMID 34526901, 2021). "Furthermore, STAT3 induced by IL‐6 trans‐signalling pathway mediate the fibroblasts of the peritoneal stroma contributed to peritoneal fibrosis." (PMID 38780509, 2024). "However, excessive or dysregulated immune responses mediated by IL-6 can also contribute to the chronic inflammation and tissue damage seen in peritoneal dialysis-related complications and peritoneal fibrosis." (PMID 38689325, 2024). "IL‐6 trans‐signalling plays an important role in peritoneal fibrosis." (PMID 38780509, 2024). "We previously observed elevation of IL-6 and macrophage infiltration in peritoneal fibrosis rats." (PMID 35784347, 2022). "In our previous study, we reported that blockade of IL-6 trans-signaling could attenuate peritoneal fibrosis by inhibiting the activation of Smad2/3, with reduced expressions of α-smooth muscle actin (α-SMA) and collagen type I (Col I) in a mouse model." (PMID 36035388, 2022). "We aimed to investigate the mechanism by which IL-6 regulated the peritoneal fibrosis." (PMID 34526901, 2021). "Since an abundant expression of inflammatory cytokines and chemokines is essential for the development and progression of peritoneal fibrosis, we further evaluated the effect of TA on the expression of some inflammatory cytokines and chemokines, including IL-6, IL-1β, TNF-α and MCP-1 by ELISA." (PMID 29179471, 2017). "In this study, we first assessed the effect of TA on the IL-6-induced change of the phenotype and the mobility of HPMCs and further investigated the signaling regulatory mechanism, in order to provide evidence for future clinical trials in the field of peritoneal fibrosis." (PMID 34526901, 2021). "Beyond TGF-β/Smad signaling, SIRT1 mitigates inflammation through deacetylation of the NF-κB p65 subunit, thereby reducing the expression of tumor necrosis factor α (TNF-α) and interleukin 6 (IL-6), both critical mediators of EMT and peritoneal fibrosis." (PMID 41009597, 2025). "LPS exposure in mouse peritoneum initiates the release of several inflammatory cytokines, including IL-1β, IL-6, and TNF-α, leading to further peritoneal fibrosis." (PMID 39728104, 2024). "In our previous work, we demonstrated that that IL‐6 trans‐signalling activates STAT3 in HPMCs and participates in the MMT process to promote peritoneal fibrosis." (PMID 38780509, 2024). "Several inflammatory pathways are involved in the peritoneal fibrosis such as NOD-like receptor protein 3 (NLRP3), Toll-like receptor (TLR), NF-κB, interleukin (IL)-1β, IL-6, IL-17, and other cytokines." (PMID 35784347, 2022).